PPARG (peroxisome proliferator activated receptor gamma)
Diseases named in the same sentence as PPARG in open-access papers (continued):
Sharing a sentence is not in itself a finding about the gene and the disease.
type 2 diabetes (continued). "PPARγ is activated by several naturally occurring compounds, and synthetic molecules, such as thiazolidinediones, which are actively used in the therapy of type 2 diabetes." (PMID 19300518, 2009). "In addition, SNPs from PPARG, KCNJ11, CDKAL1, IDE-KIF11-HHEX, IGF2BP2 and SLC30A8 were also moderately associated with type 2 diabetes, with ORs ranging from 1.114 to 1.282 (P<0.05)." (PMID 19862325, 2009). "PPARγ is a therapeutic target that has been exploited fortreatment of type II diabetes mellitus (T2DM) with agonist drugs.Since PPARγ is expressed by many hematopoietic, mesodermal andepithelial cancers, agonist drugs were tested and shown to haveboth preclinical and clinical anticancer activities." (PMID 18779871, 2008). "Genetic and pharmacologic studies in cells, rodent models, and human patients corroboratedthat the PPARγ protein serves as a masterregulator of adipocyte and macrophage function in normal and pathophysiologicalconditions (inflammation, type-2 diabetes, obesity, atherosclerosis)." (PMID 18596912, 2008). "Four SNPs were associated (p < 0.05) with quantitative traits but were not in LD (r2 < 0.03) with PPARG P12A (rs1801282), the variant previously associated with type 2 diabetes." (PMID 17903298, 2007). "Historically, PPARγ is recognized as a critical transcription factor in the regulation of adipocyte differentiation and genes involved in energy storage and utilisation, and PPARγ agonists (rosiglitazone, pioglitazone) are currently in clinical use for the treatment of Type II diabetes." (PMID 16519808, 2006). "Also, there are reports that PPARΥ (peroxisome proliferator-activated receptor gamma) antagonists, pioglitazone and rosiglitazone, which are used to treat type 2 diabetes and metabolic syndrome, equally show an increase in circulating α-Klotho in animal models." (PMID 40943475, 2025). "The therapeutic targeting of peroxisome proliferator-activated receptor gamma (PPARγ) for type 2 diabetes (T2D) remains a double-edged sword: while thiazolidinediones are efficacious, their severe side effects necessitate the discovery of safer modulators." (PMID 41368574, 2025). "Furthermore, additional studies have suggested that DMY may alleviate type 2 diabetes by inhibiting the phosphorylation of PPARγ and ERK." (PMID 40076792, 2025). "The upregulation of PPARγ and adiponectin, key regulators of glucose and lipid metabolism, suggests that M. oleifera extracts may improve insulin sensitivity and help restore normal glucose levels in patients with type 2 diabetes." (PMID 39458951, 2024). "Moreover, BCAA was implied to modulate lipid accumulation by regulating the activity of the mTOR signal pathway, and several studies suggest that the nuclear receptor peroxisome proliferator-activated receptor γ (PPARγ) modulates BCAA metabolism to interrupt type 2 diabetes." (PMID 35745155, 2022). "A peroxisome proliferator-activated receptor-gamma (PPAR) agonist called rosiglitazone (RGZ) is clinically used to treat type 2 diabetes mellitus (T2DM)." (PMID 36114448, 2022). "Thus, MMPP, as a PPARγ agonist, may be a potential drug for type 2 diabetes and metabolic disorders, which may help increase adipogenesis and insulin sensitivity." (PMID 36339572, 2022). "Troglitazone, rosiglitazone, and pioglitazone are PPARγ agonists used for treatment of type 2 diabetes mellitus (T2DM)." (PMID 33498245, 2021). "The thiazolidinediones (TZDs) are synthetic activators of PPARγ that induce insulin sensitization as a treatment for type 2 diabetes mellitus (T2DM)." (PMID 30008738, 2018). "From a clinical perspective, these TZD drugs act as full agonists of PPARγ and are highly effective oral medications for the treatment of type 2 diabetes mellitus (T2DM)." (PMID 28128331, 2017).
type 2 diabetes (continued). "PPARγ, expressed in the adipose tissue, regulates adipocyte differentiation and insulin sensitization, playing a key role in the regulation of lipid metabolism in mature adipocytes and macrophages, with a direct impact on type 2 diabetes, dyslipidemia, atherosclerosis, and cardiovascular diseases." (PMID 28208577, 2017). "It is well known that PPARG may be involved in controlling adipocytes differentiation, regulating energy homeostasis, influence of cellular cholesterol homoeostasis, and the development of type 2 diabetes mellitus (T2DM) and obesity." (PMID 29246001, 2017). "To date, most studies have evaluated the role of PPARγ in major metabolic organs such as liver, adipocytes, pancreas, or skeletal muscles, leading to target PPARγ for the treatment of type 2 diabetes with the development of the thiazolidinedione (TZD) class of drugs." (PMID 28947679, 2017). "Missense mutations in PPARγ LBD caused by nsSNPs may induce profound phenotypic changes in affected individuals, contributing to the risk of onset of various pathological states, like dyslipidemia, type 2 diabetes, and cancer." (PMID 28208577, 2017). "Thiazolidinediones (TZDs) are synthetic ligands and potent activators of PPARγ; they have been amply used in treating type 2 diabetes (T2D) in the past." (PMID 27483259, 2016). "Thus, F12016 is a potential PPARγ-targeting drug for the treatment of type 2 diabetes." (PMID 25827822, 2015). "Considering that the PPARG expression regulates lipid and glucose metabolism, insulin action and adipocyte differentiation the effect of cardiorespiratory fitness on PPARG may contribute to the prevention of future metabolic diseases in adults such as type 2 diabetes." (PMID 25879043, 2015). "PPARγ is also the target of high affinity, synthetic thiazolidinedione pharmacological ligands, including rosiglitazone and pioglitazone, which are employed clinically to stimulate PPARγ and enhance insulin sensitivity in selected patients with type 2 diabetes." (PMID 26451838, 2015). "In conclusion, a range of PPARγ activating natural products and plant extracts were recently described that bear a good potential to be further explored for therapeutic effectiveness as well as to be studied as potential dietary supplements to counteract the metabolic syndrome and type 2 diabetes." (PMID 25083916, 2014). "A majority of genes associated with type 2 diabetes from this meta-analysis (ADCY5, CDKAL1, CDKN2A/B, HHEX, IGF2BP2, SLC30A8, TCF7L2 and KCNQ1) are involved in pancreatic beta cell function, while two are implicated in insulin sensitivity (PPARG) and adiposity (FTO)." (PMID 25145545, 2014). "Because the chemical PPARγ ligands thiazolidinediones have been used widely for the treatment of type 2 diabetic patients, many of whom experience vascular diseases, clarifying the precise role of PPARγ in defective placental angiogenesis may be of clinical significance." (PMID 24926269, 2014). "For example, antidiabetic drugs of the thiazolidinedione family are believed to target the transcription factor PPARG to improve insulin sensitivity in type 2 diabetes (T2D) and induce glucose transporter 4 mRNA expression in fat and muscle." (PMID 25197274, 2014). "The peroxisome proliferator-activated receptor-gamma (PPARy) agonist, pioglitazone, belongs to the insulin-sensitizing group of drugs, which is used in the treatment of type 2 diabetes mellitus (T2DM)." (PMID 26171320, 2014). "Of great clinical interest, synthetic ligands of PPARγ, belonging to the class of thiazolidinediones (TZDs), such as troglitazone, pioglitazone, and rosiglitazone, function as insulin sensitizers and are used for treating hyperglycemia in patients with type 2 diabetes." (PMID 24790595, 2014). "Therefore, p-F11 is a novel partial PPARγ agonist, which might have the potential to be developed as a new PPARγ-targeted therapeutics for type 2 diabetes." (PMID 24454336, 2013).
type 2 diabetes (continued). "As PPARγ transrepressional activity is involved in the repression of proinflammatory cytokines and chemokines, it is tempting to think that part of TZDs therapeutic properties on type-2 diabetes could be explained by their anti-inflammatory properties." (PMID 23577023, 2013). "Thus, p-F11 is a potential PPARγ-targeted drug for the treatment of type 2 diabetes." (PMID 24454336, 2013). "Collectively, the present study demonstrated an inhibitory effect of PPARγ activation on renal mPGES-1/PGE2/EP4 pathway in type-2 diabetes and suggested that mPGES-1 may potentially serve as a therapeutic target for treating type-2 diabetes-associated DN." (PMID 24489534, 2013). "Therefore, developing agents able to disconnect the transactivational activity of PPARγ from its transrepressional activity may represent an effective strategy to treat different inflammatory diseases such as type-2 diabetes." (PMID 23577023, 2013). "Thus, it is evident that PPARγ might contribute to protumorigenic process by inducing angiogenesis during the therapy for type II diabetes." (PMID 23213321, 2012). "Therefore we examined the possibility that direct AT2 receptor stimulation by compound 21 (C21) might contribute to possible insulin-sensitizing/anti-diabetic effects in type 2 diabetes (T2DM) with PPARγ activation, mainly focusing on adipose tissue." (PMID 23155382, 2012). "Thiazolidinediones (TZDs) act through PPARγ to elicit increased sensitivity to insulin in type 2 diabetes mellitus (T2DM) and reduce inflammation in arteries." (PMID 22649490, 2012). "Thiazolidinediones/glitazones are synthetic PPARγ agonists used for treatment of type 2 diabetes mellitus (T2DM)." (PMID 21615901, 2011). "This led to the hypothesis thatinsulin sensitivity may itself play an important role in the development ofmacrovascular disease, and that agents that reduce insulin resistance, such asmetformin and PPARγ agonists,by extension, may have particular benefits in the management of type 2 diabetes." (PMID 18288280, 2008). "The peroxisome proliferator-activated receptor gamma (PPARG) gene, located on the 3p25 chromosome in type 2 diabetes, controls lipid metabolism while simultaneously affecting insulin sensitivity." (PMID 40225541, 2025). "Thiazolidinediones (TZDs: pioglitazone and rosiglitazone), which act as peroxisome proliferator-activated receptor gamma (PPAR-γ) agonists, are approved medications for type 2 diabetes, usually as second-line options." (PMID 38689985, 2024). "Pioglitazone in this review, is a PPARγ agonist (like 15d-PGJ2) that is FDA-approved to treat type-2 diabetes and can induce apoptosis in activated T-lymphocytes and anti-inflammatory effects in glial cells." (PMID 39177131, 2024). "Consistently, interactions between PPARγ and WNT/β-catenin pathways had been found in arrhythmogenic right ventricular cardiomyopathy and type 2 diabetes." (PMID 36902342, 2023). "Pioglitazone (a synthetic ligand of PPARγ) which is used clinically for the treatment of type 2 diabetes mellitus (T2DM) mitigates steatosis, inflammation, and fibrosis in subjects with NASH; however, it increases the patient’s weight and risk of bladder cancer." (PMID 37063264, 2023). "PPARγ agonists, such as TZDs, are used for type 2 diabetes mellitus (T2DM)." (PMID 37627329, 2023). "We thus aimed to develop genetic instruments for the targets of five approved type 2 diabetes medications with known mechanisms of action (sulfonylurea receptor 1 [ATP binding cassette subfamily C member 8 (ABCC8)], PPARG, SGLT2, DPP4 and GLP1R)." (PMID 37171501, 2023). "Initially, mitoNEET was identified as a mitochondrial target of thiazolidinediones such as pioglitazone and rosiglitazone, a peroxisome proliferator-activated receptor gamma (PPAR-γ) agonist, a class of medicines used to treat type-2 diabetes." (PMID 35136051, 2022).
type 2 diabetes (continued). "In addition, PPARγ activation during early-stage differentiation enhanced the differentiation of 3T3-L1 cells into white adipocytes and PPARγ activation during early-stage differentiation into white adipocytes was also enhanced in an embryonic fibroblast model of type 2 diabetes." (PMID 35725398, 2022). "PPARγ act as the core regulator of lipid metabolism, and notably influenced the concentration of BCAA in Type 2 diabetes." (PMID 35745155, 2022). "Pioglitazone hydrochloride (PGZ), a nuclear receptor peroxisome proliferator-activated receptor gamma (PPAR-γ) agonist, is a universally adopted oral agent for the treatment of type 2 diabetes (T2D)." (PMID 35677109, 2022). "An important observation in our study is that SIT acts as effectively as metformin to normalize the serum adipokine levels including leptin, resistin, adiponectin, TNF-α, IL-6, SREBP-1c and PPARγ in HFD and sucrose induced type 2 diabetic rats." (PMID 33917607, 2021). "The thiazolidinedione derivative known as Pioglitazone is a peroxisome proliferator-activated receptor gamma (PPAR-γ) agonist developed by the Takeda pharmaceutical company and approved by FDA in 1999 for management of type 2 diabetes." (PMID 34881080, 2021). "Among the many synthetic ligands, TZDs are PPARγ-selective agonists with high affinity, including troglitazone, rosiglitazone, and PIO, which are significantly effective in the treatment of type 2 diabetes and cardiovascular complications." (PMID 32190383, 2020). "In fact, the PPARγ agonist pioglitazone (PGZ), a thiazolidinedione (TZD) derivate, is used for the treatment of type 2 diabetes." (PMID 32266936, 2020). "In vivo, the PPARγ activator rosiglitazone increased the expression level of IDE and decreased Aβ levels in a mixed mouse model of AD and type 2 diabetes and alleviated the spatial learning and recognition impairments in these mice." (PMID 33128835, 2020). "The TZD drug pioglitazone, a PPARγ agonist approved by the FDA, is also known to decrease inflammatory mediators in patients with type 2 diabetes and coronary artery disease and to have favorable effects on vascular function." (PMID 30349478, 2018). "The discovery of the concept of dual integral PPARγ and FFAR1 receptor has unveiled novel methods for rational design of drugs for therapy of type 2 diabetes." (PMID 28656106, 2017). "Multiple studies have suggested that pioglitazone, a peroxisome proliferator-activated receptor γ (PPARγ) agonist, used as an insulin-sensitizing agent in the treatment of type 2 diabetes mellitus (T2DM), may have anti-atherosclerotic effects." (PMID 29037211, 2017). "PPARγ agonists of the thiazolidinedione (TZD) class are currently used for treatment of insulin resistance and type 2 diabetes." (PMID 26894429, 2016). "Rosiglitazone is a well-known PPARγ agonist that increases peripheral INS sensitivity and improves glycaemic control in type 2 diabetes." (PMID 27638500, 2016). "Other examples of successful drugs targeting genes that arise (with small effect sizes) in GWAS include PCSK9 for LDL cholesterol, and PPARG and KCNJ11 for type 2 diabetes." (PMID 26702037, 2015). "Surprisingly, we are the first to investigate the importance of PPARγ rs1801282 and KCNJ11 rs5219 for type 2 diabetes in West Africa." (PMID 24059590, 2013). "Here, we have investigated the role of three type 2 diabetes candidate SNPs well-known in other populations (TCF7L2 rs7903146, KCNJ11 rs5219, PPARγ rs1801282) in more than 1000 Ghanaians." (PMID 24059590, 2013). "Importantly, these results have bearing on the development of alternative treatments for type II diabetes as until now, the pharmacological (both beneficial and deleterious) effects of the TZD drugs have been widely linked to the peroxisome proliferator-activated receptor gamma PPARγ." (PMID 23717386, 2013).
type 2 diabetes (continued). "Emerging evidence supports yet another mechanism—PPARγ activation also induces mitochondrial biogenesis and ameliorates the impaired mitochondrial function in adipose tissues in type 2 diabetes mellitus (T2DM) patients and rodent models, demonstrated in others' and our studies." (PMID 22013433, 2011). "The best characterized PPARγ agonists are pioglitazone and rosiglitazone which are Food and Drug Administration (FDA) approved for treatment of type II diabetes and troglitazone, which has been withdrawn in 2000." (PMID 22654722, 2011). "Activities of PPARγ agonist, anti-inflammation, AMPK activator and anti-ER stress were measured in cell models and in db/db mice (a genetic animal model for type 2 diabetes)." (PMID 21375727, 2011). "In this study, we confirmed the effects of variations in PPARG, KCNJ11, CDKAL1, CDKN2A-CDKN2B, IDE-KIF11-HHEX, IGF2BP2 and SLC30A8 on type 2 diabetes." (PMID 19862325, 2009). "PPARγ agonists like rosiglitazone and pioglitazone are FDA approvedand being prescribed to millions of type-2 diabetics allover the world." (PMID 21909480, 2008). "The best characterized PPARγ agonistsare the TZDs including pioglitazone and rosiglitazone which are Food and DrugAdministration (FDA) approved for treatment of type II diabetes andtroglitazone, which was withdrawn in 2000." (PMID 18645613, 2008). "Nevertheless, rosiglitazone,a PPARγ agonist that can improve insulin sensitivity and glycemic control inpatients with type 2 diabetes, was found to increase PON1 activity, although therewas no significant change in the serum PON1 concentration." (PMID 40834279, 2025). "CBD, when used in treatment of type 2 diabetes, shows lipid and glycemic parameter improvements, which shows that CBD might have agonistic activity on PPARγ." (PMID 37111244, 2023). "In mice with type 2 diabetes induced by a high-fat diet and injection of alloxan, NAOs had the effect of improving lipid metabolism and lipid accumulation through regulation of MAPK-Nrf2 and PPARγ pathway." (PMID 37858097, 2023). "As current therapies are not well designed, novel PPARγ agonists that regulate adipogenesis must be investigated to control type 2 diabetes and other obesity-related health problems." (PMID 36339572, 2022). "Importantly, activation of PPARγ via pioglitazone (PIO), a drug used to treat type 2 diabetes, restores lipid synthesis and IFN-γ production in those intratumoral iNKT cells, and significantly enhances anti-tumor efficacy of iNKT cell-based immunotherapy." (PMID 31974378, 2020). "The present study hypothesizes that TDQ, acting as a PPARγ agonist and a DGAT2 inhibitor, not only alleviate glucose and lipid metabolism disorder but also ameliorate IR in type 2 diabetic rats." (PMID 31019978, 2019). "Activation of PPARγ in adipose tissue induces the expression of genes for fatty acid transport and storage as well as promotes de novo adipogenesis so that PPARγ activator thiazolidinediones (TZD) has been widely used in treatment of type II diabetes." (PMID 29565812, 2018). "While endogenous ligands of PPARγ include fatty acids and eicosanoids, synthetic full agonists of the receptor, including members of the thiazolidinedione (TZD) class, have been widely prescribed for the treatment of type II diabetes mellitus (T2DM)." (PMID 26435709, 2015). "However, also the thiazolidinediones (TZDs), a class of insulin sensitizers that are approved for the treatment of type 2 diabetes and have been shown to decrease steatosis in patients with NASH, function as high affinity PPARγ agonists." (PMID 23431284, 2013).